MAP3K6 (mitogen-activated protein kinase kinase kinase 6)
Description:
Component of a protein kinase signal transduction cascade. Activates the JNK, but not ERK or p38 kinase pathways.
Synonyms: ASK2; MAPKKK6; MEKK6
Tractability: Small molecule: a high-quality ligand is known; it belongs to a druggable protein family. Antibody: the Human Protein Atlas places it where antibodies can reach. PROTAC: ubiquitination databases record sites on it; a small molecule that binds it is known.
Target class: STE protein kinase ASK; Kinase; Enzyme; STE protein kinase STE11 family; STE protein kinase group; Protein Kinase
Gene: Protein-coding gene on chromosome 1 (27,355,180 to 27,366,972, reverse strand). Ensembl gene ENSG00000142733.
Subcellular location (Human Protein Atlas): Nucleoplasm; Actin filaments; Cytosol; Plasma membrane
Gene Ontology:
Molecular function: ATP binding; magnesium ion binding; MAP kinase kinase kinase activity; protein binding; protein kinase activity; protein serine kinase activity
Biological process: protein phosphorylation; JNK cascade; p38MAPK cascade; signal transduction; MAPK cascade
Genetic constraint (gnomAD): Loss-of-function variants: 106 observed, 145.73 expected, observed/expected ratio (o/e) 0.73, 90% interval 0.62 to 0.86. The upper end of that interval is the gene's LOEUF score, 0.86, which puts it in group 3 of 6, group 1 being the genes least tolerant of losing a copy. Missense variants: 1,569 observed, 1,685.8 expected, observed/expected ratio (o/e) 0.93, 90% interval 0.89 to 0.97. Synonymous variants: 695 observed, 708.86 expected, observed/expected ratio (o/e) 0.98, 90% interval 0.92 to 1.04.
Homologues: Orthologues: chimpanzee MAP3K6 (99% identical), macaque MAP3K6 (97% identical), pig MAP3K6 (89% identical), dog MAP3K6 (89% identical), mouse Map3k6 (87% identical), rat Map3k6 (87% identical), guinea pig MAP3K6 (83% identical), rabbit MAP3K6 (81% identical), zebrafish si:ch211-1i11.3 (49% identical), Drosophila melanogaster Ask1 (35% identical), Caenorhabditis elegans nsy-1 (34% identical). Paralogues in human: MAP3K5 (47% identical), MAP3K15 (45% identical).
Diseases named in the same sentence as MAP3K6 in open-access papers:
MAP3K6 is named in the same sentence as 31 diseases in open-access papers, as found by Europe PMC text mining. Sharing a sentence is not in itself a finding about the gene and the disease. The quoted sentences say what the papers report.
gastric cancer (7 papers, 2014 to 2025). A primary or metastatic malignant neoplasm involving the stomach. "Germline variants in MAP3K6 are often related to gastric cancer while limited data are present for any link to melanoma." (PMID 40072281, 2025). "For example, MAP3K6 germline mutations have also been associated with familial gastric cancer, and the gastric cancers associated with MAP3K6 predominantly have a signet ring cell morphology, although a minor glandular component has been described." (PMID 30568591, 2018). "Four individuals with gastric cancer from a Maritime Canadian family were found to carry a heterozygous variant in the MAP3K6 gene, leading to a p.P946L amino acid change." (PMID 25340522, 2014). "Somatic mutations in MAP3K6 have also been identified in other, non-gastric cancers, including ovarian (p.T968I) and breast cancers (p.P869T, p.S648L, p.Q672*))." (PMID 25340522, 2014). "Recently also CTNNA1 and MAP3K6 are described as putative gastric cancer predisposition genes, but in the majority of cases the underlying genetic cause remains unknown." (PMID 26700889, 2016). "Further, somatic mutations and altered expression of MAP3K6 in sporadic cancers and gastric cancer cell lines may suggest MAP3K6 as a potential therapeutic target for exploration." (PMID 25340522, 2014). "Our results demonstrate that inherited mutations in MAP3K6 may predispose individuals to gastric cancer; however, regulation of this pathway could have a broader role in both sporadic gastric cancers and carcinogenesis in general that warrants further investigation." (PMID 25340522, 2014). "Our experimental results showed that salidroside promoted the expression of miR-1343-3p in gastric cancer cells and down-regulated the expression of MAP3K6 and MMP24 mRNA genes significantly." (PMID 38436092, 2024). "miR-1343-3p binds the target mRNA genes MAP3K6 and MMP24 in gastric cancer cells, and then suppresses the expression of MAP3K6 and MMP24, inhibiting the proliferation and invasion of cancer cells." (PMID 38436092, 2024). "Salidroside is likely to suppress the growth of gastric cancer by up-regulating the tumor suppressor miR-1343-3p and down-regulating the expression of MAP3K6 and MMP24 signal molecules." (PMID 38436092, 2024). "Although the role of MAP3K6 in gastric cancer is unclear, the function of MAP3K6 is likely to be correlated with the development of gastric cancer." (PMID 38436092, 2024). "Expression of MAP3K6 is variable in many human tumors, with expression most significantly reduced in gastric cancer tumors compared to healthy gastric tissue, whereas MAP3K5 expression is increased." (PMID 25340522, 2014). "Salidroside may suppress the growth of gastric cancer by up-regulating the expression of the tumor suppressor miR-1343-3p and down-regulating the expression of MAP3K6 and MMP24 signal molecules." (PMID 38436092, 2024). "Next-generation sequencing of unexplained young or familial gastric cancer cases without CDH1 mutations revealed that CTNNA1, MYD88, and MAP3K6 had deleterious mutations associated with gastric cancer." (PMID 36741258, 2023). "Somatic mutations in MAP3K6 have been reported in screens of a panel of 532 kinase genes in apparent non-familial gastric cancer cases (p.S291L), as well as in two gastric cancer cell lines (N87 cells: p.R375Q, and IM95 cells: p.P958T)." (PMID 25340522, 2014). "Immunohistochemistry further clarified the expression of MAP3K6, MMP24, and STAT3 in gastric cancer cells after salidroside treatment." (PMID 38436092, 2024). "We found that the MAP3K6 and MMP24 signal molecules were regulated by miR-1343-3p in gastric cancer cells, and miR-1343-3p was negatively correlated with the expression of these signal molecules." (PMID 38436092, 2024). "In order to verify the expression of miR-1343-3p, MAP3K6, and MMP24 in gastric cancer cells after treatment with salidroside, we conducted quantitative PCR and immunostaining assay." (PMID 38436092, 2024).
gastric cancer (continued). "Our results showed that salidroside significantly down-regulated the expression of MAP3K6 and STAT3 genes in gastric cancer cells, indicating that salidroside suppressed the proliferation and progression of gastric cancer cells by inhibiting the expression of these pathway molecules." (PMID 38436092, 2024). "Both individuals, 1845 and 2447, with the phenotypically distinct gastric cancer were negative for the MAP3K6 SNV." (PMID 25340522, 2014).
breast carcinoma (5 papers, 2012 to 2024). "These loci include MAP3K6, which encodes a mitogen-activated protein kinase, a signaling transduction molecule involved in the progression of aggressive breast cancer subtypes." (PMID 33684137, 2021). "Among the candidate CpGDMs, we found eight genes with differential methylation previously associated with breast cancer susceptibility and pathology in the G2SBC and COSMIC Databases (AMOTL1, CDCP1, CYFIP1, MAP3K6, MIB2, SDK1, TAL1, and TYROBP)." (PMID 33145876, 2021). "Hypermethylation of CYFIP1 gene (only CpGDM hypermethylated in patients) was observed in patients with breast cancer (P = 2.22 × 10−12), while MAP3K6 and MIB2 gene promoters showed a slight hypomethylation in BCP." (PMID 33145876, 2021). "We also found two transcription factors (ROCK2, USF3) in the distal components of the CTRL- and MAP3K6-associations with survival; both transcription factors are interconnected within the MAPK pathway, known to be involved in breast cancer proliferation." (PMID 33684137, 2021). "For example, in breast cancer ADAM12 (rank #153) and MAP3K6 (rank #205) were recently reported to be associated with breast cancer oncogenesis." (PMID 22952662, 2012).
Familial gastric cancer (3 papers, 2014 to 2018). An autosomal dominant inherited adenocarcinoma that arises from the gastric mucosa and is characterized by the presence of poorly cohesive malignant cells and absence of glandular formations. "Mutations in MAP3K6 were only discovered in the individuals meeting the criteria for diffuse gastric cancer." (PMID 25340522, 2014).
lung carcinoma (2 papers, 2024 to 2025). "This indicates that the expression of CDK6 and MAP3K6 was elevated during the transformation of normal cells into lung cancer cells." (PMID 40278596, 2025). "Therefore, by combining TMT labeling-based proteomic analysis with previous findings, we explored the roles of CDK6 and MAP3K6 in lung cancer development and the relationship between YTHDF1, CDK6, and MAP3K6." (PMID 40278596, 2025). "Immunohistochemical staining (IHC) experiments on clinical lung cancer tissues using tissue microarrays demonstrated a positive correlation between YTHDF1 and its downstream proteins, CDK6 and MAP3K6." (PMID 40278596, 2025). "The experimental data indicated that YTHDF1, MAP3K6, and CDK6 were significantly over-expressed in lung cancer compared to adjacent normal tissues (p < 0.05)." (PMID 40278596, 2025). "Therefore, we conclude that YTHDF1 regulates CDK6 and MAP3K6 through m6A in B[a]P-induced HBE-P35 and A549 cells, providing a potential target for lung cancer treatment." (PMID 40278596, 2025).
cardiomyopathy (1 paper, 2014). A disease of the heart muscle or myocardium proper. "MAP3K6 regulates VEGF expression, and its expression was altered in a mouse model of cardiomyopathy." (PMID 25033284, 2014).
melanoma (1 paper, 2025). A malignant, usually aggressive tumor composed of atypical, neoplastic melanocytes. "In addition to the variants in the indexes, we also detected a pathogenic MAP3K6 variant in a melanoma‐diagnosed cousin in family A05." (PMID 40072281, 2025). "One family member with melanoma (not index case) carried a pathogenic variant in MAP3K6." (PMID 40072281, 2025).
Obesity (1 paper, 2009). Accumulation of substantial excess body fat. "Some genes in this subnetwork, such as Arntl, Dbp, Per1, and Per2, are known to associate with obesity traits, while other genes, such as Map3k6 and Tsc22d3, represent novel factors." (PMID 19463160, 2009).
prostate carcinoma (1 paper, 2023). A carcinoma that arises from epithelial cells of the prostate gland. "Our analysis associated low expression of MAP3K6 with better progression-free survival thus suggesting other than the tumor suppressor role for MAP3K6 in PCa and that MAP3K6 inhibition could suppress tumor growth also in prostate cancer." (PMID 36809527, 2023).
skin cancer (1 paper, 2014). "In mice, where MAP3K6 is normally expressed in gastric tissue and skin, the loss of MAP3K6 in homozygous knockout mice was found to increase susceptibility to induced skin cancer." (PMID 25340522, 2014).
skin tumors (1 paper, 2014). "The mice did not develop cancer spontaneously; however, chemical induction performed in the presence of an inflammatory stimulus led to a greater number of skin tumors in the MAP3K6 deficient mice than in control animals." (PMID 25340522, 2014).
cancer (9 papers, 2014 to 2025). A tumor composed of atypical neoplastic, often pleomorphic cells that invade other tissues. "Wnt family member 10B (WNT10B) and mitogen-activated protein kinase kinase kinase 6 (MAP3K6) associated with progression-free survival in our analysis belong to widely studied and cancer related WNT and MAPK gene families." (PMID 36809527, 2023). "Based on conservation, predicted pathogenicity and a known role of the gene in cancer predisposition, MAP3K6 was considered a strong candidate and was investigated further." (PMID 25340522, 2014). "Here we present the first evidence that germline mutations in MAP3K6 are linked to inherited cancer." (PMID 25340522, 2014). "A mutation identified in MAP3K6 (c.[2837C>T];[ = ], p.P946L) was considered a strong candidate based on the known associations of other MAP kinases with cancer, and several publications elucidating a role for MAP3K6 in tumorigenesis." (PMID 25340522, 2014). "Our experiments also indicated that CDK6 and MAP3K6 are involved in regulating cancer cell proliferation, invasion, migration, wound healing, and cell cycle progression." (PMID 40278596, 2025). "MAP3K6 expression has been reported to be reduced in cancer and acting as a tumor suppressor by enhancing proapoptotic activities in response to stress." (PMID 36809527, 2023). "This is consistent with experiments in MAP3K6 knock-out mice where cancer was only observed after the administration of both a carcinogen and an inflammatory agent, suggesting that the presence of additional stimuli are required." (PMID 25340522, 2014). "Previous studies on the role of MAP3K6 in cancer are contradictory." (PMID 36809527, 2023). "Although MAP3K6 mutations have not previously been identified in inherited cancer, there is a growing body of evidence that MAP3K6 has an important role in cancer pathogenesis." (PMID 25340522, 2014). "This is the first report of a heritable cancer resulting from SNVs in MAP3K6." (PMID 25340522, 2014). "Further analysis of WES data revealed additional variants in common cancer‐related genes involved in DNA replication and DNA damage (e.g., ATM, CDKN1A), cell polarization (SCRIB), proliferation (RNASEL), VEGF expression (MAP3K1, MAP3K6), and in genes encoding growth factors (FGF2) (Table EV2)." (PMID 32667137, 2020). "Upregulation of the metabolic genes (ALDH18A1, CAD, CHKA, POLD4, PSPH, and SQLE) and aberrant expression of cancer-related genes (ALCAM, ITGA6, DDIT3, MAP3K6, and PAK1) were found in mouse fed with high-fat-high-cholesterol similar to human NASH-HCCs." (PMID 31795276, 2019). "We demonstrated for the first time the aberrant expression of cancer-related genes (ALCAM, ITGA6, DDIT3, MAP3K6 and PAK1) and metabolism-related genes (ALDH18A1, CAD, CHKA, POLD4, PSPH, SQLE and CFD) in human NASH-HCCs." (PMID 30367044, 2018). "The S-phase arrest observed in A549 cells, but not in HBE-P35 cells, was attributed to MAP3K6 knockdown, possibly because HBE-P35 cells did not undergo sufficient malignant transformation, and MAP3K6 primarily promoted the cell cycle in cancer cells." (PMID 40278596, 2025). "The results showed that salidroside could significantly up-regulate the expression of miR-1343-3p, and significantly down-regulate the expression of MAP3K6 and MMP24 genes in cancer cells." (PMID 38436092, 2024). "No putative pathogenic mutations in other cancer predisposition genes among which CTNNA1 and MAP3K6 were detected." (PMID 26700889, 2016). "The age of onset varied among MAP3K6 SNV carriers in the five families, and one had not developed cancer even at late stage of life, suggesting incomplete penetrance." (PMID 25340522, 2014).
tumor (9 papers, 2009 to 2024). "We next used the DNA isolated from a tumorous section of the FFPE sample of the affected MAP3K6 SNV carrier 1884 (the proband) to screen for additional somatic SNVs or loss of heterozygosity (LOH) within the tumor itself." (PMID 25340522, 2014). "Beyond that, although we found no significantly different levels of expression of MAP3K6 between the tumor and the normal tissues, we only could identify a single study which suggested that MAP3K6 may be involved in the dynamics underlying self-renewal and differentiation of tumor progenitor cells." (PMID 35311629, 2022). "Surprisingly, salidroside significantly up-regulated the expression of tumor suppressor miR-1343-3p, and down-regulated the expression of MAP3K6, STAT3 and MMP24-related genes." (PMID 38436092, 2024). "Still, MAP3K6 inhibition is reported to suppress tumor growth, vessel formation and VEGF expression." (PMID 36809527, 2023). "Somatic mutations were excluded in the complete coding sequence and intron-exon boundaries of MAP3K6 in the proband's tumor." (PMID 25340522, 2014). "A somatic second-hit variant (p.H506Y) was present in DNA obtained from one of the tumor specimens, and evidence of DNA hypermethylation within the MAP3K6 gene was observed in DNA from the tumor of another affected individual." (PMID 25340522, 2014). "Tumor-promoting roles of MAP3K6, PAK1, ALCAM and ITGA6 have been reported, thus their upregulation may also function in the development of NASH-related HCC." (PMID 30367044, 2018). "Lack of LOH at the MAP3K6 gene could also be inferred in this tumor, as both wild-type and mutant alleles could be identified at the germline mutation site." (PMID 25340522, 2014). "The mRNA genes of mitogen activated protein kinase kinase kinase 6 (MAP3K6)/membrane matrix metalloproteinase 24 (MMP24) signal molecules, which are closely related to tumor proliferation and migration, were significantly down-regulated." (PMID 38436092, 2024). "Five genes, CACNB4 (FCMSS 0.65), MAP3K6 (FCMSS 0.66), CD14 (FCMSS 0.66), CACNA2D4 (FCMSS 0.66), and MAP4K4 (FCMSS 1.52) had slightly stronger FC for MSS-specific tumors than for all tumor combined (FCoverall 0.67, 0.73, 0.68, 0.67, and 1.47, respectively)." (PMID 29636593, 2018).
mitochondrial disease (1 paper, 2025). "Eight patients had IBGC (variants in SLC20A2, PDGFB, MYORG), 4 had mitochondrial disease (MT-TL1), and 2 had monogenic vascular conditions (GAL, MAP3K6)." (PMID 40947452, 2025).
MAP3K6 also shares sentences with these, for which no sentence is quoted: infection (4 papers); atherosclerosis (2); colorectal cancer (2); ovarian carcinoma (2); calcification (1); cardiac hypertrophy (1); diabetes (1); diabetic neuropathy (1); esophageal squamous cell carcinoma (1); Fabry disease (1); genetic disorders (1); leukemia (1); malignant glioma (1); Myelodysplasia (1); papilloma (1); pneumonia (1); Stroke (1); vitiligo (1).